BCL2L15 (BCL2 like 15)
Synonyms: Bfk; C1orf178; FLJ22588
Tractability: No criterion of Open Targets' tractability assessment is met for any kind of drug.
Gene: Protein-coding gene on chromosome 1 (113,876,816 to 113,887,581, reverse strand). Ensembl gene ENSG00000188761.
Gene Ontology:
Molecular function: protein binding
Biological process: regulation of apoptotic process
Cellular component: cytosol; nucleus
Genetic constraint (gnomAD): Loss-of-function variants: 15 observed, 18.72 expected, observed/expected ratio (o/e) 0.8, 90% interval 0.54 to 1.23. The upper end of that interval is the gene's LOEUF score, 1.23, which puts it in group 5 of 6, group 1 being the genes least tolerant of losing a copy. Missense variants: 180 observed, 210.94 expected, observed/expected ratio (o/e) 0.85, 90% interval 0.75 to 0.97. Synonymous variants: 58 observed, 72.68 expected, observed/expected ratio (o/e) 0.8, 90% interval 0.64 to 0.99.
Homologues: Orthologues: chimpanzee BCL2L15 (99% identical), macaque BCL2L15 (91% identical), dog BCL2L15 (82% identical), pig BCL2L15 (76% identical), mouse Bcl2l15 (71% identical), rat Bcl2l15 (70% identical), rabbit BCL2L15 (67% identical).
Diseases named in the same sentence as BCL2L15 in open-access papers:
BCL2L15 is named in the same sentence as 14 diseases in open-access papers, as found by Europe PMC text mining. Sharing a sentence is not in itself a finding about the gene and the disease. The quoted sentences say what the papers report.
autoimmune thyroid disease (2 papers, 2016 to 2021). Inflammatory disease of the thyroid gland due to autoimmune responses leading to lymphocytic infiltration of the gland. "The credible set also included two eQTLs for BCL2L15, a weakly proapoptotic protein associated with autoimmune thyroid disease and type 1 diabetes, in T helper cells." (PMID 33574239, 2021).
colorectal cancer (2 papers, 2018 to 2021). A primary or metastatic malignant neoplasm that affects the colon or rectum. "MiR-144 was markedly down-regulated in colorectal cancer cells and suppressed the expression of GSPT1 to regulate the cell proliferation-related gene expressions of c-myc, survivin and Bcl2L15 and metastasis-related factor MMP28." (PMID 30126852, 2018).
endophthalmitis (1 paper, 2021). An infectious process affecting the internal structures of the eye. "Furthermore, BCL2L15 (B-cell lymphoma 2) which is an amplifier of the apoptotic signal was also differentially expressed in MDR-PA induced endophthalmitis." (PMID 35046947, 2021).
hypothyroidism (1 paper, 2025). Abnormally low levels of thyroid hormone. "For example, genetically predicted plasma levels of ALDH2, BCL2L15, WASL, POLR2F, and ADPGK were positively associated with hypothyroidism risk, while H2BC21 and H2BC26 showed negative associations." (PMID 40868097, 2025).
mastitis (1 paper, 2020). Inflammation of breast tissue during lactation or postpartum due to an obstructed duct or infection. "Comparison with indigenous pigs showed genes that were associated with mastitis resistance (ARHGAP39, ARPC4, PHC2, and BCL2L15) and hair follicle development (FOXN1)." (PMID 32457791, 2020).
Obesity (1 paper, 2021). Accumulation of substantial excess body fat. "RT-PCR analysis showed downregulation of FOLH1, ALAS2 and LOC100855540 genes, and upregulation of BCL2L15 gene, suggesting that the metabolic difference between normal and mild to moderate obesity was involved in the hemoglobin metabolism." (PMID 34258471, 2021). "In current study, the expression of BCL2L15 and FOLH1 in the mild to moderate obesity groups were shown in the significant changes compared to those in control group, whereas those genes were not belonged with the specific metabolic pathway in PBMC prepared form obese dogs." (PMID 34258471, 2021).
cancer (2 papers, 2021 to 2022). A tumor composed of atypical neoplastic, often pleomorphic cells that invade other tissues. "The analysis of YY1 and BCL2L15 expression following CRC samples stratification based on cancer aggressiveness (i.e., metastasis vs. primary, mesenchymal vs. epithelial) was demonstrated to be a significant discriminator." (PMID 34445183, 2021). "Given their observed anti-cancer role, we propose YY1 and BCL2L15 as candidate diagnostic and prognostic CRC biomarkers." (PMID 34445183, 2021). "Alternatively, YY1 could recruit enzymes able in turn to modify the chromatin (es., EZH2, HDAC) and, hence, orchestrate changes in the epigenetic status of the BCL2L15 gene, as it was observed in other cancer and non-cancer models." (PMID 34445183, 2021).
tumor (2 papers, 2021 to 2022). "CRC single-cell sequencing dataset analyses demonstrated higher co-expression levels of both YY1 and BCL2L15 within defined tumor cell clusters." (PMID 34445183, 2021). "CRC dataset analyses corroborated a tumor-suppressive role for both YY1 and BCL2L15 whose expressions were inversely correlated with aggressiveness." (PMID 34445183, 2021). "In conclusion, our study uncovered the tumor-suppressive role of YY1 and BCL2L15, and their potential value as biomarkers useful in both diagnosis and prognosis of CRC patients." (PMID 34445183, 2021). "Importantly, within the other non-tumor cells (stromal, myeloid, B and T cells) only YY1 was expressed, while BCL2L15 was sparsely detected." (PMID 34445183, 2021). "By selectively looking into the epithelial tumor cellular component and stratifying the hierarchical clusters based on the CMS, it was possible to observe a heterogeneous expression of both YY1 and BCL2L15." (PMID 34445183, 2021).
bacterial infection (1 paper, 2025). "Second, the Basal.MUC16 cluster showed a significant increase (adjusted p < 0.05) in genes associated with bacterial infection (PDZD3, SFTPA2, PIK3C2B), cytokine signaling (TRIM31, SERPINB2), and apoptosis (BCL2L15, VIL1)." (PMID 39935174, 2025).
gastrointestinal tumors (1 paper, 2016). "Reduction in BCL2L15 protein expression is observed in gastrointestinal tumors." (PMID 27486433, 2016).
BCL2L15 also shares sentences with these, for which no sentence is quoted: idiopathic pulmonary fibrosis (2 papers); Graves disease (1); Hashimoto thyroiditis (1); type 1 diabetes (1).